LDHA (lactate dehydrogenase A)
Diseases named in the same sentence as LDHA in open-access papers (continued):
Sharing a sentence is not in itself a finding about the gene and the disease.
heart failure (8 papers, 2020 to 2025). Inability of the heart to pump blood at an adequate rate to meet tissue metabolic requirements. "Cardiac pressure overload can significantly upregulate LDHA expression in the heart, and LDHA deficiency in cardiomyocytes can lead to defective cardiac hypertrophy and heart failure." (PMID 37938421, 2023). "LDHA has been studied as a therapeutic target for diseases such as heart failure, atherosclerosis, and hypertension." (PMID 40800583, 2025). "The present study shows that SIL exerts cardioprotective effects by modulating the HIF-1α-glycolytic pathway, leading to the downregulation of key glycolytic enzymes (GLUT1, PFKFB3, LDHA) and the restoration of metabolic homeostasis in heart failure." (PMID 40944191, 2025). "LDHA, plays a critical role in converting pyruvate to lactate, a process that is enhanced in heart failure." (PMID 39605071, 2024). "Although we observed a slight increase in LDHA expression, the lactate concentration in cardiomyocytes was decreased during heart failure." (PMID 37443257, 2023). "In Ang II-induced heart failure, LDHA-cKO mice displayed a significant reduction in α-MHC K1897 lactylation compared with LDHA-cWT mice." (PMID 37443257, 2023). "To further elucidate the role of LDHA in Ang II-induced heart failure, we administered Ang II into LDHA-cKO mice." (PMID 37443257, 2023). "If LDHA is the main mediator of α-MHC K1897 lactylation, loss of LDHA should be observed during heart failure." (PMID 37443257, 2023). "LDHA‐inhibited mice showed exacerbated heart failure, while sodium lactate or MCT4 inhibitors could upregulate α‐MHC‐K1897la and improve heart failure." (PMID 40984037, 2025). "Indeed, it was shown that TAC induces a metabolic shift towards glycolysis in WT mice, although cardiomyocytes-restricted deletion of LDHA induces heart failure." (PMID 40659490, 2025). "Interestingly, though LDHA expression was slightly increased in heart failure, lactate concentration in H9c2 cells and myocardial tissues was decreased." (PMID 37443257, 2023). "The effects of LDHA on α-MHC K1897 lactylation were next explored in Ang II-induced heart failure." (PMID 37443257, 2023). "Correspondingly, compared with LDHA-cWT mice, LDHA-cKO mice showed a weaker α-MHC–Titin interaction, which was significantly decreased in Ang II-induced heart failure." (PMID 37443257, 2023). "Our results identify four factors, p300, SIRT1, LDHA, and the intracellular lactate concentration, as regulators of α-MHC K1897 lactylation during heart failure." (PMID 37443257, 2023). "In this study, silybin was shown to alleviate post-myocardial infarction heart failure by downregulating HIF-1α expression and inhibiting its nuclear translocation, which, in turn, reduces the HIF-1α-mediated upregulation of key glycolytic enzymes (PFKFB3, GLUT1, LDHA)." (PMID 40944191, 2025). "Importantly, slightly increased expression of LDHA in mice with heart failure suggests that LDHA may not be the core manipulator in the reduction in α-MHC K1897 lactylation during heart failure." (PMID 37443257, 2023).
prostate tumors (8 papers, 2019 to 2025). "Additionally, lactate dehydrogenase A (LDHA) chain has shown overexpression in prostate tumors." (PMID 39125581, 2024). "Decreased expression of SIRT5 and consequently enhanced levels of LDHA succinylation on LDHA-K118, were found to negatively correlate with the survival rates of patients as the hyper-succinylation enhanced its activity and exacerbated prostate tumour proliferation and migration." (PMID 38213532, 2023). "When TRAMP mice were given 6 μmol/mouse (1 mg/mouse) three times a week for 17–19 weeks, the prostate tumor expression of glycolysis-promoting enzymes such as hexokinase II (HKII), pyruvate kinase M2 (PKM2) and lactate dehydrogenase A (LDHA) was decreased by 32–45%." (PMID 37108142, 2023). "Lactate dehydrogenase-A (LDHA), a protein subunit of the highly lactate-favoring LDH isoform muscle-type 5 (LDH-5), catalyzes the reduction of pyruvate to lactate and is overexpressed in many cancers, including prostate tumors." (PMID 30813322, 2019).
renal carcinoma (8 papers, 2021 to 2026). A carcinoma arising from the epithelium of the renal parenchyma or the renal pelvis. "Identifies possible targets for treatment in the interactions between FKBP10 and LDHA to prevent metabolic reprogramming in renal cancer and increase the effectiveness of HIF2α inhibitors." (PMID 39968078, 2025). "Used in vivo studies, bioinformatics, and molecular biology methods to investigate the relationship between FKBP10 and LDHA and how it affects the course of renal cancer as well as treatment sensitivity." (PMID 39968078, 2025). "Analyzes the ways in which FKBP10 impacts the response to HIF2α inhibitors and the development of renal cancer by increasing histone lactylation and enhancing LDHA phosphorylation." (PMID 39968078, 2025). "In view of the importance of LDHA in the Warburg effect, we believe that the orientation of LDHA in the catalytic conversion of pyruvate and lactic acid in renal cancer is the focus of current research." (PMID 34604067, 2021). "Particularly, transcriptional program for a mesenchymal MMP-dependent motility (i.e., EMT) is triggered in myocardial cells through Snail1 lactylation following myocardial infarction as well as in thyroid and renal carcinomas through LDHA- or Sirtuin 1-dependent mechanisms." (PMID 40434517, 2025). "Recently published data demonstrated that endogenous lactate dehydrogenase A (LDHA) was upregulated in renal carcinoma cells and promoted EphA2 overexpression in cancer-derived exosomes, which promoted M2 macrophage polarization through the activation of the PI3K/AKT/mTOR and tumor progression." (PMID 39596256, 2024). "Therefore, we explored the relationships between PD-L1 levels and glucose metabolism related enzymes (GLUT1, HK2, and LDHA) in renal cancer, which showed that only LDHA levels correlated positively with PD-L1 levels." (PMID 36267974, 2022). "At the molecular level, we found that SLC2A1, LDHA, GOT1, and GOT2 were regulated by HGD and GSTZ1 to alter the glucose uptake and energy metabolism of renal cancer cells." (PMID 35562974, 2022).
Alzheimer disease (7 papers, 2010 to 2023). A progressive, neurodegenerative disease characterized by loss of function and death of nerve cells in several areas of the brain leading to loss of cognitive function such as memory and language. "Its activity is increased in Alzheimer's disease patients' brains, and mRNA levels of LDHA are higher in fibroblasts derived from late-onset Alzheimer's disease patients versus controls." (PMID 33977265, 2021). "Recent studies have shown that the glycolytic enzymes PDK1 and LDHA are primarily expressed within neurons of the frontal cortex and hippocampus of wild-type and transgenic Alzheimer’s disease mice." (PMID 30809587, 2019). "Overexpression of PDK1 and LDHA have been shown to protect against neuronal death by reducing mitochondrial respiration and ROS production and maintaining ATP levels in a model of Alzheimer’s disease characterized by mitochondrial dysfunction." (PMID 25963727, 2016). "Research showed that Aβ-resistant nerve cells displayed increased PDK1 expression, enhanced lactate dehydrogenase A (LDHA) activity and reduced mitochondrial ROS, suggesting the potential anti-apoptotic roles of the PDK-lactic acid axis in the surviving neurons of the Alzheimer’s disease (AD) brain." (PMID 37935660, 2023). "For example, Newington and co-workers have shown that the overexpression of LDHA in a rat B12 cell line conveys resistance to amyloid β and other neurotoxins, which may elucidate why some people tolerate high levels of amyloid β deposition without the development of Alzheimer’s disease." (PMID 32830860, 2020).
cardiac hypertrophy (7 papers, 2021 to 2025). "Expression of LDHA is induced during physiological (e.g., running and swimming) and pathological (e.g., pressure overload induced by thoracic aortic constriction) cardiac hypertrophy." (PMID 34722687, 2021). "Mice with cardio-specific deletion of LDHA, the M-type (muscle) subunit that forms a home- or hetero-tetramer of functional LDH, were characterized with defective cardiac hypertrophy and functional failure under pressure overload." (PMID 39594567, 2024). "Up to now, studies have discovered various proteins that regulate cardiac hypertrophy, like YAP and LDHA." (PMID 39038022, 2024). "Conversely, inhibition of lactate production using glycolysis inhibitor (2‐DG), LDH inhibitor (oxamate) and LDHA inhibitor (GNE‐140) reduces HKla levels and inhibits the development of cardiac hypertrophy." (PMID 39205384, 2024).
esophageal squamous cell carcinoma (7 papers, 2016 to 2026). Esophageal squamous cell carcinoma (ESCC) is a type of esophageal carcinoma (EC) that can affect any part of the esophagus, but is usually located in the upper or middle third. "Studies aimed at investigating subcellular localization of LDHA have reported cytoplasmic and nuclear localization of LDHA in some cancers such as esophageal squamous cell carcinoma." (PMID 33996536, 2021). "Yao et al51 found that LDHA expression was up‐regulated in clinical samples of esophageal squamous cell carcinoma, and LDHA knockdown could inhibit cell growth and migration in vitro and impair tumorigenesis in vivo." (PMID 30403008, 2018). "Moreover, our study delineates a novel pathway in esophageal squamous cell carcinoma whereby STIP1 enhances the interaction between AHCY and LDHA, enabling AHCY to recruit PRMT3 to methylate LDHA at R106." (PMID 41163796, 2025). "Our study identifies a novel mechanism of LDHA post‐translational activation through methylation at R106 by AHCY‐recruited PRMT3, revealing a previously unknown layer of glycolytic regulation that promotes esophageal squamous cell carcinoma progression." (PMID 41163796, 2025).
myocardial infarction (7 papers, 2021 to 2025). Gross necrosis of the myocardium, as a result of interruption of the blood supply to the area, as in coronary thrombosis. "These proteins included several important blood biomarkers like the indicators for myocardial infarction LDHA/LDHB, the coagulation factor F7, the liver injury marker CPS1, the infection marker CRP, the metabolic syndrome marker FABP534 and the inflammatory predictor GSN35." (PMID 34373457, 2021). "Here we found that the expression of nuclear LDHA was induced both in the infarct area of myocardial infarction (MI) in mice and hypoxic cardiomyocytes in vitro." (PMID 40710803, 2025). "Therefore, manipulating macrophage metabolism—whether by inhibiting critical enzymes in glycolysis, like LDHA, or promoting fatty acid oxidation—could be an effective way to modulate macrophage polarization and improve outcomes in myocardial infarction." (PMID 41583440, 2025).
cervical tumors (6 papers, 2018 to 2025). "In mouse cervical tumors, lactate dehydrogenase A (LDHA), as an enzyme involved in energy metabolism, is abnormally translocated to the cell nucleus due to the increase of intracellular ROS caused by HPV-16 E7." (PMID 38956668, 2024). "Liu reported that LDHA is preferably located in the nucleus in cervical tumors due to HPV-induced intracellular ROS accumulation." (PMID 37298317, 2023). "Expectedly, immunohistochemistry experiments showed LDHA protein was significantly up-regulated in human cervical tumor tissues." (PMID 33645623, 2021). "Here we show that lactate dehydrogenase A (LDHA) preferably locates in the nucleus in HPV16-positive cervical tumors due to E7-induced intracellular reactive oxygen species (ROS) accumulation." (PMID 30356100, 2018). "LDHA undergoes nuclear translocation in a variety of tumors including cervical tumors." (PMID 39587076, 2024).
colorectal tumor (6 papers, 2015 to 2025). "LDHA reinforces the Warburg effect, providing colorectal tumour cells with a metabolic advantage that increases their chance of survival while facilitating invasion." (PMID 28516914, 2017). "Proteins that regulate glycolysis (PGK1, PGAM1, ENO1, PKM, TKT), ammonia detoxification (GLUD1), and other metabolic pathways (LDHA, GAPDH, MDH2) were reported to be differentially expressed in mouse xenograft colorectal tumor models with different radio- responsiveness." (PMID 38410100, 2024). "However, in colorectal tumor cells, curcumin downregulated the expression and activity of hexokinase II (HKII) in a concentration-dependent manner and had little effect on other key glycolytic enzymes, PFK, PGM, and LDHA." (PMID 36831394, 2023).
esophageal cancer (6 papers, 2014 to 2024). A primary or metastatic malignant neoplasm involving the esophagus. "We revealed for the first time that LDHA inhibition blocks TNF-α-induced migration of esophageal cancer cells and effectively inhibits MMP9 expression in cells stimulated with TNF-α by attenuating activation of the ERK1/2-related signaling pathway." (PMID 36555705, 2022). "Our results highlight the efficacy of SO in inhibiting lactic acid production by esophageal cancer cells and thus show that the use of an LDHA inhibitor can be considered in the design of adjuvant therapy for esophageal cancer patients." (PMID 36555705, 2022). "To assess whether TNF-α is involved in the regulation of LDH in esophageal cancer cells, we analyzed the expression levels of genes encoding LDH subunits (LDHA and LDHB) in TNF-α-treated KYSE150 and EC7 cells versus untreated cells using qPCR." (PMID 36555705, 2022). "In immunohistochemical images of esophageal cancer tissues from patients, we observed high staining intensity for LDHA but variable intensity within the same clusters of tumor cells, which may be related to their degree of differentiation." (PMID 36555705, 2022). "Therefore, the purpose of this work was to address the question of whether inhibition of LDHA activity may affect the pro-migratory effects of TNF-α in esophageal cancers, with particular attention to the role of MMP9." (PMID 36555705, 2022). "Esophageal cancer cells preferentially metabolize glucose, and express high levels of glycolytic enzymes such as PKM2 and Lactate dehydrogenase A (LDHA), which contribute to the invasion, metastasis, and poor outcome." (PMID 27384996, 2016).
kidney cancer (6 papers, 2014 to 2026). Primary or metastatic malignant neoplasm involving the kidney. "On the other hand, it was also proven that LDHA inhibition results in increasing apoptosis of the tumor cells in FH-deficient kidney cancer and is considered in therapeutic strategy for patients with kidney cancer." (PMID 24885701, 2014). "Integration of LDHA appears to be a useful additional way to identify poor prognosis in kidney cancer patients." (PMID 24885701, 2014). "In accordance with the protein expression, we observed increased LDHA mRNA levels in kidney cancer compared with normal renal cortex in 162 of 170 patients (95%)." (PMID 24885701, 2014). "Overall, the search results suggest that LDHA may be a useful biomarker for predicting the prognosis and monitoring the progress of kidney cancer, particularly RCC." (PMID 38201450, 2023). "The correlation between LDHA expression and the tumor grade should be interpreted with caution because the current system of kidney cancer grading relies on assigning the grade of the tumor according to the area of the highest grading not according to the grading of the majority of the tumor." (PMID 24885701, 2014). "Lactate dehydrogenase A (LDHA), a key enzyme in glycolysis, has been studied as a potential biomarker in kidney cancer." (PMID 38201450, 2023).
liver fibrosis (6 papers, 2019 to 2025). "Subsequently, MIG1 reduced the transcription of LDHA and HK2, which blocked glycolysis-mediated macrophage M1 polarization to mitigate liver fibrosis-associated inflammation." (PMID 40864752, 2025). "In liver fibrosis, the Gly28 residue of lactate dehydrogenase A (LDHA) binds to HIF-1α to form a complex, which enhances the expression of glycolysis-related genes, thereby promoting aerobic glycolytic reprogramming during HSC activation." (PMID 40421024, 2025). "The existing literature has shown that PKM2 and LDHA can regulate glycolysis, affecting the polarization function of macrophages and interfering with liver fibrosis." (PMID 38202819, 2024). "Hence, it is anticipated that LDHA and H3K18la could serve as promising targets for the therapeutic intervention of macrophage polarization in the context of liver fibrosis, specifically in relation to the administration of Sal B." (PMID 38202819, 2024). "Later experiments demonstrated that the suppression of lactate dehydrogenase A (LDHA) obstructed H3K18 lactylation and positively regulated liver fibrosis by inhibiting HSC proliferation, motility, and ECM deposition." (PMID 39974732, 2025). "The classic Wnt/β-catenin signaling pathway promotes HSCs glycolysis by upregulating LDHA and HIF-1α, which exacerbates liver fibrosis." (PMID 40421024, 2025). "It was found that knockdown of LDHA reduced H3K18 lactylation levels by decreasing SOX9 transcription, which in turn diminished HSC activation and extracellular matrix deposition, and alleviated liver fibrosis in rats." (PMID 40421024, 2025). "Furthermore, the overexpression of SOX9 significantly alleviated the effects of LDHA silencing on activated HSCs, suggesting that SOX9 operates downstream of H3K18 lactylation in the promotion of liver fibrosis." (PMID 39974732, 2025).
pancreatic adenocarcinoma (6 papers, 2021 to 2026). "In addition, LDHA also promotes cancer cell proliferation and invasion across membranes in vitro and enhances tumor growth and metastasis in a murine pancreatic adenocarcinoma orthotopic model." (PMID 41368023, 2025). "As an LDHA inhibitor, berberine plays a critical role in suppressing LDHA/AMPK-mTOR-mediated pancreatic adenocarcinoma progression." (PMID 36407005, 2022).
squamous cell carcinoma (6 papers, 2016 to 2026). A carcinoma arising from squamous epithelial cells. "Importantly, the levels of salivary LDHA in patients with squamous cell carcinoma of the tongue and lower oral cavity were significantly higher than other patients affected with squamous cell carcinoma in other parts of the head and neck." (PMID 31737570, 2019). "It was reported that STAT1 upregulated the key glycolytic enzymes lactate dehydrogenase A (LDHA) and pyruvate kinase type M2 (PKM2), promoted the productivity of glycolysis, and then enhanced the resistance to RT in SCC61 human squamous cell carcinoma." (PMID 36313645, 2022).
Burkitt lymphoma (5 papers, 2016 to 2024). A rare form of malignant mature B-cell non-Hodgkin lymphoma. "Furthermore, we conducted immunohistochemical (IHC) staining to compare the protein expression of PKM and LDHA between the lymph node of Burkitt lymphoma (BL) and normal controls." (PMID 38099309, 2023). "Serum lactate dehydrogenase A (LDH-A), which is an enzyme converting pyruvate to lactate, is commonly elevated in aggressive NHL cases, such as DLBCL and Burkitt’s lymphoma, and it has been used as a prognostic indicator for overall survival." (PMID 30818878, 2019). "Interestingly, c-MYC was reported to transactivate LDHA promoter in c-MYC-transformed human lymphoblastoid cells and Burkitt lymphoma cells." (PMID 37791390, 2024). "Lactate dehydrogenase A (LDH-A), which is frequently overexpressed in numerous human cancers, was also identified as a MYC target gene in fibroblasts, and its over-expression was shown to be required for MYC-mediated transformation of human lymphoblastoid cells and Burkitt lymphoma cells." (PMID 28362357, 2017).